MAP1A (microtubule associated protein 1A)
Description:
Structural protein involved in the filamentous cross-bridging between microtubules and other skeletal elements.
Synonyms: MAP1L; MTAP1A
Tractability: PROTAC: ubiquitination databases record sites on it; its protein half-life has been measured.
Gene: Protein-coding gene on chromosome 15 (43,510,958 to 43,531,620, forward strand). Ensembl gene ENSG00000166963.
Subcellular location: Cytoplasm, cytoskeleton
Subcellular location (Human Protein Atlas): Cytosol; Mid piece; Principal piece
Gene Ontology:
Molecular function: protein binding; actin binding; cytoskeletal anchor activity; microtubule binding; structural molecule activity; tau protein binding; tubulin binding; ionotropic glutamate receptor binding
Biological process: anterograde axonal protein transport; associative learning; axonogenesis; dendrite development; memory; microtubule cytoskeleton organization; negative regulation of proteasomal ubiquitin-dependent protein catabolic process; negative regulation of protein localization to microtubule; neuron cellular homeostasis; neuron projection maintenance; positive regulation of protein localization; positive regulation of protein localization to cell surface; regulation of microtubule depolymerization; regulation of synaptic plasticity; retrograde axonal protein transport; voluntary musculoskeletal movement
Cellular component: axon; axon initial segment; cytoplasm; cytosol; dendrite; dendritic branch; dendritic microtubule; dendritic shaft; microtubule; microtubule associated complex; neuron projection; neuronal cell body; primary dendrite; synapse; axon cytoplasm; cytoskeleton; photoreceptor outer segment; postsynaptic density
Genetic constraint (gnomAD): Loss-of-function variants: 42 observed, 196.01 expected, observed/expected ratio (o/e) 0.21, 90% interval 0.17 to 0.28. The upper end of that interval is the gene's LOEUF score, 0.28, which puts it in group 1 of 6, group 1 being the genes least tolerant of losing a copy. Missense variants: 2,994 observed, 3,622.7 expected, observed/expected ratio (o/e) 0.83, 90% interval 0.8 to 0.85. Synonymous variants: 1,229 observed, 1,407.2 expected, observed/expected ratio (o/e) 0.87, 90% interval 0.83 to 0.92.
Homologues: Orthologues: chimpanzee MAP1A (99% identical), macaque MAP1A (95% identical), pig MAP1A (85% identical), dog MAP1A (85% identical), rabbit MAP1A (84% identical), mouse Map1a (80% identical), rat Map1a (80% identical), guinea pig MAP1A (78% identical), tropical clawed frog map1a (39% identical), zebrafish map1ab (33% identical), zebrafish map1aa (30% identical). Paralogues in human: MAP1B (24% identical), MAP1S (11% identical).
Diseases named in the same sentence as MAP1A in open-access papers:
MAP1A is named in the same sentence as 45 diseases in open-access papers, as found by Europe PMC text mining. Sharing a sentence is not in itself a finding about the gene and the disease. The quoted sentences say what the papers report.
schizophrenia (4 papers, 2016 to 2026). A major psychotic disorder characterized by abnormalities in the perception or expression of reality. "Microtubule-associated proteins (MAPs) with differential abundance in schizophrenia encompassed microtubule-associated proteins 1A (MAP1A), 2 (MAP2), and tau (MAPT), and dynamin 1 (DNM1)." (PMID 26909022, 2016). "The MAP1A variant, which is crucial for axon and dendrite development and has been implicated in autism spectrum disorder and schizophrenia, may contribute to the severe psychiatric phenotype by influencing synaptic plasticity, a process also affected by the 22q11.2 deletion." (PMID 39189429, 2024). "Around 50% and around 30% of the association signal, for MAP1A and for ANO8, respectively, was driven by rare deleterious variants in individuals diagnosed with ADHD only (without comorbid schizophrenia, ID or autism), whereas the ANK2 signal was driven mainly by ADHD with co-occurring autism or ID." (PMID 41224997, 2026).
autism spectrum disorder (3 papers, 2024 to 2026). A spectrum of developmental disorders that includes autism, and Asperger syndrome. "Protein-truncated variants in MAP1A were recently related to the presence of autism spectrum disorder (ASD) and attention-deficit/hyperactivity disorder (ADHD) in a large cohort." (PMID 39156017, 2024). "MAP1A, encoding microtubule‐associated protein 1A, is crucial for axon and dendrite development and has been implicated in autism spectrum disorder and SCZ." (PMID 39189429, 2024).
bladder cancer (3 papers, 2021 to 2024). "Accumulation of Map1a was also found in differentiating embryonal carcinoma cells, and Map1a is also an emerging marker of bladder cancer." (PMID 38570783, 2024). "In vitro and in vivo experiments will be performed in the future to explain the pathways of MAP1A in the development of bladder cancer." (PMID 36408130, 2022). "To our knowledge, this is the first time we predict and report the correlation of MAP1A with early diagnosis of bladder cancer, prognosis, immunotherapy, and the ceRNA network." (PMID 36408130, 2022). "After differential expression and survival analysis using the GEPIA and GETx databases, MAP1A was confirmed to have the strongest correlation with the prognosis of early-stage bladder cancer." (PMID 36408130, 2022). "We retrieved the PubMed database and Web of Science database for current studies focused on the relationship between MAP1A and bladder cancer." (PMID 36408130, 2022). "MAP1A is considered as a prospective biomarker for early diagnosis, therapeutic observation, and prognosis analysis in bladder cancer." (PMID 36408130, 2022). "Limma package in R was used to identify genes correlated with miR-34a-5p and MAP1A in bladder cancer tissues." (PMID 36408130, 2022). "This study assessed the gene MAP1A expression in bladder cancer and correlated to the survival bioinformatically from TCGA and GEO databases and verified by differential gene expression and survival analysis using the GEPIA database." (PMID 36408130, 2022). "The MAP1A gene was decreased in bladder cancer tissues compared with high levels in normal bladder samples." (PMID 36408130, 2022). "Further, in vitro confirmation of MAP1A expression at the cellular level was done using bladder cancer cell lines SW780 and 5637, as well as normal bladder epithelial cells SV-HUC-1." (PMID 36408130, 2022). "As shown in the results of our study on the correlation between MAP1A and immunotherapy, MAP1A is also possible to be a biomarker for monitoring immunotherapy response in bladder cancer." (PMID 36408130, 2022). "MAP1A was significantly correlated with overall survival and disease-free survival rates in bladder cancer (P < 0.001)." (PMID 36408130, 2022). "Normal bladder samples from GEPIA and GETx databases were used to verify MAP1A gene expression in comparison to bladder cancer tissues." (PMID 36408130, 2022). "High expression of MAP1A was noted in normal bladder tissues with a decreased expression in bladder cancer tissues." (PMID 36408130, 2022). "Collectively, these results supported the idea that the MAP1A/miR-34a-5p/LINC0667/circ_MYLK/circ_MAP1B ceRNA network may play a role in the pathological processes of bladder cancer." (PMID 36408130, 2022). "Finally, further clinical investigation is aimed at confirming the interaction between MAP1A and bladder cancer stage and grading." (PMID 36408130, 2022). "Additionally, MAP1A is correlated with a poor prognosis of bladder cancer (P < 0.001), with an approximately 26% ~ 55% of 5-year survival rate." (PMID 36408130, 2022). "As a result, it was hypothesized that the miR-34a-5p mediated MAP1A ceRNA regulation network that promotes autophagy to induce bladder cancer develops through the PIK3-AKT-mTOR pathway." (PMID 36408130, 2022). "Significant correlations between MAP1A and OS (P < 0.001, HR = 1.9) as well as DFS (P < 0.05, HR = 1.7) in bladder cancer were identified through gene expression profiling interactive analysis (GEPIA), indicating MAP1A may be a high-risk factor." (PMID 36408130, 2022). "In order to predict whether MAP1A can be used to guide bladder cancer immunotherapy, we also analyzed the correlation of MAP1A with immune cells and immune checkpoints." (PMID 36408130, 2022). "Finally, we preliminarily tested MAP1A expression in bladder cancer cell lines." (PMID 36408130, 2022). "In vitro, bladder cancer cell lines (SW780, 5637) and normal bladder epithelial cell SV-HUC-1 were verified for MAP1A expression." (PMID 36408130, 2022).
bladder cancer (continued). "The present work reports for the first time that the gene MAP1A could be a potential biomarker in the early diagnosis, prognosis, and immunotherapy of low-grade bladder cancer (non-muscle invasion and superficial muscle invasion stages)." (PMID 36408130, 2022).
Parkinson disease (3 papers, 2011 to 2025). A progressive degenerative disorder of the central nervous system characterized by loss of dopamine producing neurons in the substantia nigra and the presence of Lewy bodies in the substantia nigra and locus coeruleus. "MAP1A is frequently investigated in the context of neurodegenerative diseases, including Alzheimer’s and Parkinson’s." (PMID 39980838, 2025).
prostate carcinoma (3 papers, 2015 to 2022). A carcinoma that arises from epithelial cells of the prostate gland. "Previous literature indicated that these six genes, i.e., CAV1, COL4A2, HSPB1, ITGB3, MAP1A and MCAM, were linked to prostate cancer progression." (PMID 26158290, 2015). "MAP1A was also reported to be a prognostic biomarker in prostate cancer." (PMID 34221960, 2021). "In this study, we selected six genes, that had additionally been independently reported to be related to prostate cancer progression, CAV1, COL4A2, HSPB1, ITGB3, MAP1A and MCAM." (PMID 26158290, 2015).
Ataxia (2 papers, 2024). Ataxia refers to impaired coordination of voluntary muscle movement. "For instance, mutations of the Map1 gene, nm2719, that disrupt the Map1a gene lead to cerebral Purkinje cell degeneration, due to degeneration of neuronal microtubules, causing tremors and ataxia as manifested by poor muscle control that causes difficulty with walking and balance." (PMID 38570783, 2024). "MAP1A deficiency has been linked to neurodegeneration such as ataxia, tremors, and late-onset degeneration of cerebellar Purkinje cells, but its role in cancers remains unclear." (PMID 39129004, 2024). "Furthermore, spontaneous mutation of nm2719 that disrupts the Map1a gene in mice displayed the phenotypes of tremors and ataxia, affecting coordination, balance, and speech due to the loss of cerebellar Purkinje neurons in these adult mice." (PMID 38570783, 2024).
depression (2 papers, 2022 to 2024). "Furthermore, considerably reduced expression of Map1a was detected in the hippocampus of patients with major depressive disorder during post-mortem examination by qPCR." (PMID 38570783, 2024).
melanoma (2 papers, 2022 to 2023). A malignant, usually aggressive tumor composed of atypical, neoplastic melanocytes. "To investigate whether dieckol regulated autophagy in A375 melanoma cells, we examined the protein levels of two autophagy markers, microtubule-associated protein 1A/1B-light chain 3 beta (LC3B) and sequestosome 1 (p62)." (PMID 36430634, 2022).
22q11.2 deletion syndrome (1 paper, 2024). 22q11.2 deletion syndrome (DS) is a chromosomal anomaly which causes a congenital malformation disorder whose common features include cardiac defects, palatal anomalies, facial dysmorphism, developmental delay and immune deficiency. "We report a case of a 61‐year‐old female with 22q11.2 deletion syndrome (22q11.2DS) and a novel heterozygous nonsense variant in MAP1A, identified through whole‐genome sequencing (WGS)." (PMID 39189429, 2024).
atherosclerosis (1 paper, 2024). A disease characterized by the build-up of fatty material and calcium deposition in the arterial wall resulting in partial or complete occlusion of the arterial lumen. "To determine if atherosclerosis regression and/or trehalose activate autophagy, we performed immunostaining of aortic roots with the autophagosome marker microtubule-associated protein 1A/1B-light chain 3 (LC3)." (PMID 38433753, 2024).
bladder tumor (1 paper, 2022). "The expression levels of a portion of feature genes, such as ANGPTL2, CAV1, FNBP1, FXD6, MAP1A, and ZCCHC24 were significantly decreased in bladder tumor cell lines." (PMID 35719407, 2022).
dementia (1 paper, 2024). Loss of intellectual abilities interfering with an individual's social and occupational functions.
diabetes (1 paper, 2024). "Future studies should be conducted to validate our finding regarding the association between MAP1A and complications of diabetes and HT." (PMID 39459569, 2024).
Dyslipidemia (1 paper, 2024). "This suggests that metabolic syndrome might lead to too much of the microtubule-associated protein 1a." (PMID 39459569, 2024).
Huntington disease (1 paper, 2022). Huntington disease (HD) is a rare neurodegenerative disorder of the central nervous system characterized by unwanted choreatic movements, behavioral and psychiatric disturbances and dementia. "When comparing the striatal phosphoproteome of Huntington’s disease and WT mice in the EE condition, only one phosphopeptide (MAP1A, Threonine 1633) was upregulated in Huntington’s disease compared with WT mice." (PMID 36523271, 2022).
Insulin resistance (1 paper, 2019). Increased resistance towards insulin, that is, diminished effectiveness of insulin in reducing blood glucose levels. "Corticotropin releasing hormone binding protein (CRHBP), ARHGEF15, MME, MAP1A, FGF13, and SHANK3 are novel biomarkers for the development of insulin resistance." (PMID 30678306, 2019).
ischemic stroke (1 paper, 2021). A stroke disorder caused by obstruction of blood flow to the brain, due to thrombotic (local blood clot formation) or embolic (due to a blood clot or other material traveling from another site) event. "The fact that the treatment with Ngb-NPs maintains MAP1a levels elevated after induction by stroke, is probably to favor its restorative activity repairing the dendrites of neurons damaged by the ischemic stroke." (PMID 35008673, 2021).
lung carcinoma (1 paper, 2021). "Significantly higher mRNA expressions of MAP1A/1B/1S/2/7/7D2 were found in lung cancer specimens in numerous datasets." (PMID 34660263, 2021).
medulloblastoma (1 paper, 2023). A malignant, invasive embryonal neoplasm arising from the cerebellum. "Of these seven genes (LTBP1, MAP1A, MBNL2, LGALS1, PNRC1, DAB2, and PLAAT3), only one, LGALS1, had been researched previously in relation to medulloblastoma, where it is up-regulated in MBSHH patients and activated by the SHH signalling pathway." (PMID 36831428, 2023).
neuroblastoma (1 paper, 2020). Neuroblastoma (NB) is the most common solid, extracranial childhood tumor. "CK2 was reported to be implicated in phosphorylation of MAP 1B, together with MAP 1A, during neuroblastoma cell differentiation." (PMID 32795331, 2020).
pancreatic cancer (1 paper, 2024). "According to the GEPIA analysis based on TCGA, similar to AGTPBP1, the expression of MYLK and MAP1A in pancreatic cancer tissues was significantly upregulated (P < 0.05)." (PMID 39129004, 2024). "The Spearman correlation analysis showed AGTPBP1 was positively correlated with the expression of MYLK and MAP1A in pancreatic cancer tissues by GEPIA analysis." (PMID 39129004, 2024).
Stroke (1 paper, 2021). Sudden impairment of blood flow to a part of the brain due to occlusion or rupture of an artery to the brain. "One of these genes in cluster 2 corresponds to Map1a, previously found as overexpressed due to stroke." (PMID 35008673, 2021). "Specifically, when comparing MCAO vs. sham, proteins FBXO7, WIPI2, NTRK2, A0A0G2JY03, and ITGB8 appeared clearly underexpressed, whereas MAP1a and CPQ were overexpressed, indicating a clear effect of the stroke (MCAO injury) on the individuals." (PMID 35008673, 2021).
cancer (4 papers, 2017 to 2024). A tumor composed of atypical neoplastic, often pleomorphic cells that invade other tissues. "Next, the limma package in R predicted MAP1A expression in pan-cancer." (PMID 36408130, 2022). "Additionally, the R language was used to analyze the expression of MAP1A in pan-cancer." (PMID 36408130, 2022). "Other drug targets for cancer therapeutics with high CAP scores include MAP4 (60%) and TUBB1 (30%), which are targets of paclitaxel, MAP1A (42%), a target of estramustine, CD3G (39%), a target of muromonab, and PARP1 (37%), a target of olaparib." (PMID 29273096, 2017).
tumor (3 papers, 2015 to 2023). "The results based on t test indicate that COL4A2, HSPB1, ITGB3, and MAP1A were significantly less expressed in tumor adjacent stroma in comparison with normal stroma (p values < 0.05)." (PMID 26158290, 2015). "Four genes (COL4A2, HSPB1, ITGB3, and MAP1A) were significantly less expressed in tumor adjacent stroma in comparison with normal stroma (p values < 0.05)." (PMID 26158290, 2015). "In validation by real-time PCR, four genes (COL4A2, HSPB1, ITGB3, and MAP1A) demonstrated significantly lower expression in tumor-adjacent stroma compared to normal stroma (p value ≤ 0.05)." (PMID 26158290, 2015). "Most strikingly, our analysis revealed a seven-gene drug-tolerant signature in all four drug-tolerant cell lines, irrespective of chemotherapeutic treatment, parental cell line and tumour subgroup—LTBP1, MAP1A, MBNL2, LGALS1, PNRC1, DAB2 and PLAAT3." (PMID 36831428, 2023).
nervous system diseases (2 papers, 2021 to 2022).
infection (1 paper, 2018). The state of being infected such as from the introduction of a foreign agent such as serum, vaccine, antigenic substance or organism. "Lastly, it is worth noticing that LTNP 006 had two variants potentially affecting HIV nuclear import by the PIK3R5 and MAP1A genes and had undeletable levels of newly integrated HIV DNA post infection, which cannot be attributed to the more common protective alleles in this LTNP." (PMID 30323326, 2018).
MAP1A also shares sentences with these, for which no sentence is quoted: neurodegenerative disease (3 papers); acute myeloid leukemia (1); attention deficit-hyperactivity disorder (1); autism (1); brain glioma (1); breast carcinoma (1); ciliopathy (1); dyslexia (1); embryonal carcinoma (1); fibrosarcoma (1); glioblastoma (1); glioma (1); high grade glioma (1); HIV-1 infection (1); immune diseases (1); mental illness (1); pancreatic ductal adenocarcinoma (1); Parkinson’s (1); scrapie (1).